LRRC8B (leucine rich repeat containing 8 VRAC subunit B)
Description:
Non-essential component of the volume-regulated anion channel (VRAC, also named VSOAC channel), an anion channel required to maintain a constant cell volume in response to extracellular or intracellular osmotic changes. The VRAC channel conducts iodide better than chloride and can also conduct organic osmolytes like taurine. Channel activity requires LRRC8A plus at least one other family member (LRRC8B, LRRC8C, LRRC8D or LRRC8E); channel characteristics depend on the precise subunit composition.
Synonyms: TA-LRRP; KIAA0231; TALRRP
Tractability: Antibody: UniProt places it where antibodies can reach, with high confidence; its Gene Ontology location is reachable by antibodies, with high confidence; UniProt predicts a signal peptide or a membrane-spanning region. PROTAC: its protein half-life has been measured.
Gene: Protein-coding gene on chromosome 1 (89,524,829 to 89,597,861, forward strand). Ensembl gene ENSG00000197147.
Subcellular location: Cell membrane; Endoplasmic reticulum membrane
Pathways (Reactome):
Transport of small molecules: Miscellaneous transport and binding events
Gene Ontology:
Molecular function: protein binding; volume-sensitive anion channel activity
Biological process: monoatomic anion transmembrane transport; aspartate transmembrane transport; cyclic-GMP-AMP transmembrane import across plasma membrane
Cellular component: cytoplasm; monoatomic ion channel complex; plasma membrane; endoplasmic reticulum membrane
Genetic constraint (gnomAD): Loss-of-function variants: 23 observed, 59.73 expected, observed/expected ratio (o/e) 0.39, 90% interval 0.28 to 0.55. The upper end of that interval is the gene's LOEUF score, 0.55, which puts it in group 2 of 6, group 1 being the genes least tolerant of losing a copy. Missense variants: 693 observed, 981.49 expected, observed/expected ratio (o/e) 0.71, 90% interval 0.66 to 0.75. Synonymous variants: 359 observed, 394.37 expected, observed/expected ratio (o/e) 0.91, 90% interval 0.83 to 0.99.
Homologues: Orthologues: chimpanzee LRRC8B (99% identical), macaque LRRC8B (99% identical), dog LRRC8B (97% identical), rabbit LRRC8B (96% identical), guinea pig LRRC8B (96% identical), rat Lrrc8b (95% identical), mouse Lrrc8b (94% identical), pig LRRC8B (93% identical), tropical clawed frog lrrc8b (70% identical). Paralogues in human: LRRC8A (59% identical), LRRC8C (51% identical), LRRC8D (48% identical), LRRC8E (46% identical), SCRIB (16% identical), LRRD1 (15% identical), PHLPP1 (15% identical), ERBIN (14% identical), PHLPP2 (14% identical), LRRC1 (14% identical), LRRC7 (14% identical), LRRC40 (14% identical), and 19 more.
Diseases named in the same sentence as LRRC8B in open-access papers:
LRRC8B is named in the same sentence as 6 diseases in open-access papers, as found by Europe PMC text mining. Sharing a sentence is not in itself a finding about the gene and the disease. The quoted sentences say what the papers report.
Alzheimer disease (1 paper, 2023). A progressive, neurodegenerative disease characterized by loss of function and death of nerve cells in several areas of the brain leading to loss of cognitive function such as memory and language. "Although altered methylation in gene LRRC8B has not been previously reported in existing literature as differentially methylated in cord blood in regard to maternal diabetes in pregnancy, cell-type-specific methylation changes in gene of LRRC8B have been associated with Alzheimer's disease." (PMID 37029435, 2023).
cancer (1 paper, 2023). A tumor composed of atypical neoplastic, often pleomorphic cells that invade other tissues. "To date, there have been few functional studies on the LRRC8B gene, most of which have been in the field of medical research and are widely used in cancer treatment." (PMID 36833283, 2023).
LRRC8B also shares sentences with these, for which no sentence is quoted: autoimmune disease (1 paper); diabetes (1); lung carcinoma (1); tumor (1).